OGG1 (8-oxoguanine DNA glycosylase)
Diseases named in the same sentence as OGG1 in open-access papers (continued):
Sharing a sentence is not in itself a finding about the gene and the disease.
pulmonary fibrosis (continued). "Thus, the data may provide a clue to understanding a mechanism by which ROS-induced DNA damage and OGG1-BER of oxidative DNA damage play roles in pulmonary fibrosis." (PMID 36421478, 2022). "We propose that in PM2.5-induced pulmonary fibrosis, OGG1 primarily repairs damaged DNA to mitigate the disease, operating through distinct mechanisms compared to its role in BLM-induced pulmonary fibrosis." (PMID 40867876, 2025). "A bleomycin (BLM)-induced mouse pulmonary fibrosis model was established, and TH5487 (the small molecule OGG1 inhibitor) and Mitochondrial division inhibitor 1 (Mdivi-1) were used for administration." (PMID 38822247, 2024). "Administration of the OGG1 inhibitor, TH5487, which displaces 8-oxoG from the active binding site of OGG1, decreased tissue remodeling and bleomycin-induced pulmonary fibrosis in murine models." (PMID 36651270, 2023). "In contrast to the control mice, mice with pulmonary fibrosis exhibited notably higher levels of lung proteins such as TGF-βR2, SKP-1, CHI3L1, OGG1, and Galectin-3, alongside lower expression of p-4Ebp1, SARA, p-P70S6K, and PP2A." (PMID 38259493, 2023). "OGG1 modulates TGF-β1-induced cell transformation and aggravates p-Smad2/3, at least partly by interacting with Smad 7 in the process of pulmonary fibrosis." (PMID 36421478, 2022). "We discuss the emerging role for AEC mtDNA damage repair by 8-oxoguanine DNA glycosylase (OGG1) and mitochondrial aconitase (ACO-2) in maintaining mtDNA integrity, which is important in preventing AEC apoptosis and asbestos-induced pulmonary fibrosis." (PMID 26370974, 2015). "Collectively, these data support a key role for AEC OGG1 and ACO-2 in the maintenance of mtDNA necessary for preventing AEC apoptosis and pulmonary fibrosis." (PMID 26370974, 2015). "In an asbestos-induced model of pulmonary fibrosis, oxidant-induced mtDNA damage was blocked by overexpression of ACO-2, a mitochondria-targeted OGG1, and an OGG1 mutant incapable of DNA repair that chaperones ACO-2." (PMID 26370974, 2015). "OGG1 inhibition protects against pulmonary fibrosis, which is partly via activating PINK1/Parkin-mediated mitophagy and retarding M2 macrophage polarization, providing a therapeutic target for pulmonary fibrosis." (PMID 38822247, 2024). "Furthermore, additional studies are necessary to assess the translational significance of AEC OGG1 and ACO-2 in preserving mtDNA integrity and preventing pulmonary fibrosis." (PMID 26370974, 2015). "We focus on the emerging role for AEC mtDNA damage repair by 8-oxoguanine DNA glycosylase (OGG1) and mitochondrial aconitase (ACO-2) in maintaining mtDNA integrity which is important in preventing AEC apoptosis and asbestos-induced pulmonary fibrosis in a murine model." (PMID 26370974, 2015). "We also reported that oxidative stress (asbestos or H2O2) preferentially induces mtDNA than nuclear DNA damage in AEC both in vitro as well as in vivo and that OGG1 preservation of ACO-2 is crucial for preventing asbestos-induced AEC mtDNA damage, intrinsic apoptosis, and pulmonary fibrosis." (PMID 26370974, 2015). "However, the molecular mechanism of OGG1 against pulmonary fibrosis has been not elucidated completely." (PMID 38822247, 2024). "Unlike OGG1, PARP1 exhibits its consistent mechanism in pulmonary fibrosis, that is, PARP-1 inhibition may be significant." (PMID 36421478, 2022). "In PM2.5-related studies, AEC2s lacking OGG1 have lower proliferation and high NF-κB activation, which lead to hyperactivation of its downstream inflammatory gene expression and more PM2.5-induced pulmonary fibrosis in vivo." (PMID 36421478, 2022).
pulmonary fibrosis (continued). "Bleomycin-induced lung fibrosis reduces lung SIRT3 and OGG1 expression in WT but not Sirt3Tg mice." (PMID 34202229, 2021).
Alzheimer disease (15 papers, 2009 to 2025). A progressive, neurodegenerative disease characterized by loss of function and death of nerve cells in several areas of the brain leading to loss of cognitive function such as memory and language. "Polymorphic variants of OGG1 Ala53Thr and Ala288Val have reduced enzymatic activity and were found in patients with Alzheimer’s disease." (PMID 40806775, 2025). "Up-to-date studies linked a higher level of DNA damage (e.g., resulting from inactive OGG1) with Alzheimer’s disease and mutations in genes coding for subunits of complex I of ETC with Parkinson’s disease." (PMID 32575813, 2020). "Neurons from OGG1-deficient mice are sensitive to oxidative stress and reduced OGG1 levels have also been associated with Alzheimer’s disease (AD)." (PMID 31816862, 2019). "The impaired repair of oxidative lesions due to AAG SNPs could contribute to neuronal damage, similar to 8-oxoguanine DNA glycosylase (OGG1) variants in Alzheimer’s disease." (PMID 40806775, 2025). "Decreased OGG1 levels and mutations in the OGG1 gene are linked to Alzheimer’s disease." (PMID 37762489, 2023). "Additionally, it has also recently been suggested that hypomorphic alleles of hOGG1 are associated with Alzheimer's disease cases and that defects in OGG1 may play an important role in the disease in a significant number of AD patients." (PMID 19629170, 2009). "A restoration of OGG1 has been proposed in high-oxidative stress conditions, including neurological diseases such as Alzheimer’s disease." (PMID 38672428, 2024). "On the “Network” page, we selected the “ADO Ontology (BioPortal) Alzheimer's Disease Ontology” dictionary; then, the “OGG1” node was highlighted (Step 2) and expanded with the top ten enriched associated terms from the selected dictionary." (PMID 32308806, 2020). "Alzheimer’s disease (AD) has been correlated to a reduced expression of the GirK2, GirK3, GirK4, KCNQ2, and KCNQ3 subunits and genes encoding for the antioxidants SOD, 8-oxoguanine DNA glycosylase (OGG1), and monoamine oxidase A (MAO-A) in rats." (PMID 32825356, 2020). "Similarly, the same authors explored the effects of compromised OGG1 activity in a 5XFAD mouse model of Alzheimer’s disease (AD) and found an increase in 8oxo-dG in hippocampal neurons and further deficits in cognition compared to 5XFAD mice with normal OGG1 activity levels." (PMID 36204460, 2022). "A Ser326Cys polymorphism in 8-oxoguanine DNA glycosylase (Ogg1), the enzyme responsible for excision of 8-oxoguanine, is associated with sporadic ALS but not with Alzheimer’s disease." (PMID 32005289, 2020).
diabetes (15 papers, 2011 to 2023). "In this study, our data showed that Klotho deficiency may cause loss of regulation in OGG1 expression and promote the generation of ROS and DNA damage, which eventually aggravated MtD in diabetes-induced podocytes." (PMID 33162804, 2020). "In inflammation models such as endotoxic shock, diabetes and contact hypersensitivity, OGG1 gene knockout in mice was shown to be associated with decreased serum cytokine and chemokine levels, which highlights the importance of this enzyme in the inflammatory response." (PMID 26316174, 2015). "Our results further confirmed the protective roles of Klotho on diabetes-induced DNA damage of podocyte, how Klotho regulates OGG1 inhibiting 8-OHdG remains to be further studied." (PMID 33162804, 2020). "Further experimental confirmation by immunofluorescence showed STZ-induced diabetes suppressed the expression of both synapotopodin, a marker of podocyte, and OGG1." (PMID 33162804, 2020). "Our data also showed that significant decrease in OGG1 in kidney cancer patients with diabetes resulted in an accumulation and a significant amount of oxidative DNA damage, indicating the role of DNA repair enzyme in tumorigenesis." (PMID 24797175, 2014). "In this study, we provide evidence that hyperactivation of Akt/mTOR and significant decreased in tuberin resulted in significant decrease in DNA repair enzyme (OGG1) and accumulation of oxidative DNA damage in kidney cancer patients with diabetes." (PMID 24797175, 2014). "Overexpression of hOGG1 in the mitochondria can reduce FFA-induced inhibition of ATP production and reduce apoptosis of islet β cells, suggesting that OGG1 may be a new target for intervention in type 2 diabetes mellitus." (PMID 36620083, 2022). "Noteworthily, our study found Klotho deficiency may aggravate podocyte MtD for the failure of regulating ROS-induced low expression of OGG1 and deteriorate 8-OHdG-induced DNA damage in diabetes." (PMID 33162804, 2020). "Additionally, the combination of null GSTM1 and OGG1, null GSTT1 and OGG1 and GSTM1, GSTT1 and GSTP1 was revealed to be significantly associated with increased risk of diabetes in Turkish population." (PMID 29682485, 2017). "In addition, decrease in tuberin expression resulted in a significant decrease in protein expression of OGG1 and increased in oxidative DNA damage, 8-oxodG in kidney tissues from patients with cancer or cancer+diabetes." (PMID 24797175, 2014). "Of the top 15 proteins found by Cytoscape 3.6.1, 8, CAT and OGG1 (downregulated) and CASP3, COMT, CYP1B1, DPYD, NQO1, and PTGS1 (upregulated), were dysregulated in diabetes-related kidney disease." (PMID 34367469, 2021).
ovarian carcinoma (15 papers, 2013 to 2025). A malignant neoplasm originating from the surface ovarian epithelium. "In particular, the SNP rs2304277 which causes transcriptional down-regulation of the glycosylase OGG1 is associated with increased ovarian cancer risk for BRCA1 mutation carriers." (PMID 35619904, 2022). "The rs2304277 variant in the OGG1 glycosidase gene of the base excision repair pathway has been shown to increase the penetrance of ovarian cancer in patients with BRCA1/2 mutations." (PMID 33541411, 2021). "For example, the common polymorphism in OGG1 rs2304277 has been linked to BRCA1-deficiency in ovarian cancer." (PMID 31329989, 2019). "In particular, one of the most recent examples was described by our group for a SNP (rs2304277) in the OGG1 (8-guanine DNA glycosylase) gene that was associated with increased ovarian cancer risk in BRCA1 mutation carriers." (PMID 27015555, 2016). "We have recently shown that rs2304277 variant in the OGG1 glycosidase gene of the Base Excision Repair pathway can increase ovarian cancer risk in BRCA1 mutation carriers." (PMID 27015555, 2016). "In summary, we have identified at least two SNPs, rs1466785 and rs2304277, in the DNA glycolylases NEIL2 and OGG1, potentially associated with increased breast and ovarian cancer risks in BRCA2 and BRCA1 mutation carriers, respectively." (PMID 24698998, 2014). "The strongest evidence of association found in BRCA1 carriers was between rs2304277 in the OGG1 gene and ovarian cancer risk." (PMID 24698998, 2014). "In order to simulate the situation in the BRCA1-deficient ovarian tumours carrying lower OGG1 amounts, we made use primarily of the human ovarian carcinoma cell line A2780 (ECACC 93112519), which was treated with various combinations of siRNAs and subsequently with olaparib." (PMID 31329989, 2019). "Polymorphisms of other BER components, notably the glycosidase OGG1, result in an increased risk of ovarian cancer, especially in women who are BRCA1 deficient, and are a common finding with up to 63% of women with ovarian cancer carrying these germline variants." (PMID 29925418, 2018).
atherosclerosis (12 papers, 2018 to 2025). A disease characterized by the build-up of fatty material and calcium deposition in the arterial wall resulting in partial or complete occlusion of the arterial lumen. "It was also found that microRNA-33 (miRNA-33), a molecule associated with atherosclerosis, can directly inhibit the expression of human OGG1 and indirectly inhibit the expression of mouse and human OGG1 through AMP-dependent protein kinase." (PMID 40867876, 2025). "OGG1 repairs DNA damage induced by OS, and an OGG1 (rs1052133) polymorphism has been associated with atherosclerosis and CVD risk." (PMID 31223421, 2019). "For example, in mouse models of atherosclerosis, systemic lupus erythematosus, and gastrointestinal inflammation, Ogg1 deficiency exacerbates the inflammatory response and accelerates the disease process, whereas, in allergic airway inflammation and asthma, Ogg1 acts as a pro-inflammatory agent." (PMID 37372030, 2023). "Although VSMC OGG1 protected against atherosclerosis, the underlying mechanisms, which may be multiple, are unclear." (PMID 29643057, 2018). "For instance, in the context of gastrointestinal inflammation and atherosclerosis, OGG1 exhibited a capacity to impede the progression of inflammation, a phenomenon that can be attributed to the predominance of β isoforms over α isoforms." (PMID 40867876, 2025). "A mounting body of evidence suggests a potential for OGG1 to play a role in the treatment of atherosclerosis, thus offering a novel target for clinical therapeutic interventions." (PMID 40867876, 2025). "While OGG1−/−ApoE−/− mice display elevated 8oxoG and increased atherosclerotic plaque compared to control ApoE–/– mice, VSMC specific OGG1 overexpressing SM22α-OGG1 ApoE−/− mice are protected from high-fat-diet-induced atherosclerosis." (PMID 34831061, 2021). "In atherosclerosis, increased ROS and impaired OGG1-dependent DNA repair led to the activation of NLRP3 and plaque formation." (PMID 34403365, 2021). "Together, the results of this study implicate acetyltransferase p300 and deacetylase SIRT1-mediated regulation of OGG1 in controlling atherosclerosis through regulation of oxidative stress-induced cellular senescence." (PMID 34831061, 2021). "We have identified that 8oxoG repair is reduced in VSMCs in human atherosclerosis as a result of chronic oxidative stress–induced reduction in expression, stability, acetylation, and activity of OGG1." (PMID 29643057, 2018). "Atherosclerosis was increased in the descending aorta and aortic root in OGG1−/− ApoE−/− mice compared with controls but markedly decreased in both vascular beds in SM22α-OGG1 ApoE−/− mice; this protective effect was lost in SM22α-OGG1K-R ApoE−/− mice." (PMID 29643057, 2018). "Inhibiting endogenous oxidative damage by rescuing VSMC OGG1 markedly reduces atherosclerosis in vivo, an effect that requires OGG1 acetylation." (PMID 29643057, 2018). "Rescue of VSMC OGG1 prevents 8oxoG accumulation and these consequences, protecting against atherosclerosis." (PMID 29643057, 2018). "Animal experiments have also demonstrated a role for OGG1 in the development of atherosclerosis." (PMID 40867876, 2025). "Concurrently, the mechanism of action of OGG1 in atherosclerosis necessitates further study." (PMID 40867876, 2025). "Overexpression of Ogg1 significantly reduces apoptosis in the pulmonary arterial endothelial cells of mice fed with a Western diet, suggesting it as a key player in forestalling atherosclerosis." (PMID 40563431, 2025). "Given the role of endothelial dysfunction in atherosclerosis and stroke, further studies should explore whether OGG1 augmentation could serve as a therapeutic strategy for vascular disease." (PMID 40563431, 2025). "Another study found that Ogg1−/− mice had a large increase in oxidized mitochondrial DNA (ox-mtDNA) due to Ogg1 deficiency, which caused the activation of NLRP3 inflammatory vesicles and promoted IL-1β secretion, accelerating the development of atherosclerosis." (PMID 37372030, 2023).
atherosclerosis (continued). "The significance of OGG1 acetylation and its contribution in controlling atherosclerosis has been further investigated in murine models where control ApoE−/−, OGG1−/−ApoE−/−, SM22α-OGG1 ApoE−/−, and SM22α-OGG1K-R ApoE–/– mice were fed a high-fat diet for 14 weeks." (PMID 34831061, 2021). "However, chronic oxidative stress in atherosclerosis results in downregulation of p300 and p300-mediated acetylation of OGG1, which in turn reduces OGG1 protein stability and thus expression and overall 8oxoG repair activity." (PMID 29643057, 2018). "We studied levels of 8oxoG and its regulatory enzymes in human atherosclerosis, the mechanisms regulating 8oxoG repair and the base excision repair enzyme 8oxoG DNA glycosylase I (OGG1) in VSMCs in vitro, and the effects of reducing 8oxoG in VSMCs in atherosclerosis in ApoE−/− mice." (PMID 29643057, 2018). "Ogg1 deficiency in atherosclerotic mice induces larger plaque and greater amount of lipid content, while both knockout of Ogg1 and NLRP3 rescue the enhanced atherosclerosis observed in Ogg1−/− mice." (PMID 30405440, 2018). "OGG1 deficiency has been shown to cause a significant increase in oxidized mitochondrial DNA (mtDNA), which, in turn, has been linked to the activation of the NLRP3 inflammasome, the secretion of interleukin-1 beta (IL-1β), and the acceleration of atherosclerosis." (PMID 40867876, 2025). "However, such phenomena could be reversed by silencing NLRP3, indicating that OGG1 is indeed a negative regulator of atherosclerosis." (PMID 29850631, 2018). "In the cardiovascular system, the function of OGG1 has been analysed in ischemia reperfusion injury, TAC, and in atherosclerosis, using gene knockout or overexpression approaches." (PMID 35391931, 2022). "OGG1 protects VSMCs against oxidative DNA damage, cell senescence, and apoptosis and reduces atherosclerosis formation, identifying BER as a possible therapeutic target in atherosclerosis." (PMID 29643057, 2018). "Although the acetyltransferase p300 can acetylate OGG1 in cancer cells, the major acetyltransferase and deacetylase enzymes of OGG1 in VSMCs are not known, nor is their expression in atherosclerosis." (PMID 29643057, 2018). "Finally, the absence of OGG1 lowers arterial compliance and distensibility to promote vascular stiffness in aging, ultimately contributing to atherosclerosis." (PMID 40563431, 2025). "OGG1−/− mice showed increased 8oxoG in vivo and increased atherosclerosis, whereas mice expressing VSMC-specific OGG1 but not the acetylation mutant OGG1K-R showed markedly reduced intracellular 8oxoG and reduced atherosclerosis." (PMID 29643057, 2018).
gastric cancer (12 papers, 2011 to 2022). A primary or metastatic malignant neoplasm involving the stomach. "Concerning the relation between OGG1 and gastric cancer, two case–control studies showed that polymorphisms in OGG1 confer risk for gastric cancer, as did a meta-analysis with 1180 cases, and 2444 controls." (PMID 35181726, 2022). "In a preliminary search, we identified 58 research articles related to OGG1 Ser326Cys polymorphism and the risk of head and neck, oral, pancreatic, gallbladder, colorectal and gastric cancers." (PMID 27026921, 2016). "Human 8-oxoguanine DNA glycosylase (hOGG1) is known to play an important role in the prevention of carcinogenesis, including gastric cancer (GC)." (PMID 27603140, 2016). "In gastric cancer, there are elevated levels of the 8-oxoG mutagenic base, and some of the DNA repair enzymes are specific for this substrate when it is incorrectly incorporated into DNA, such as the OGG1 BER pathway." (PMID 35372019, 2022).